FSIP1 (fibrous sheath interacting protein 1)
Diseases named in the same sentence as FSIP1 in open-access papers (continued):
Sharing a sentence is not in itself a finding about the gene and the disease.
cancer (7 papers, 2015 to 2024). A tumor composed of atypical neoplastic, often pleomorphic cells that invade other tissues. "Taken together, FSIP1 can promote the proliferation, propagation, migration, and invasion of cancer cells." (PMID 38737444, 2024). "As a component of AKAP4, FSIP1 may play a role in tumor biology and thus may be a target for cancer immunotherapy." (PMID 35692888, 2022). "In addition, FSIP1 can bind to and activate cancer/testis antigen proteins (including CABYR, SPA17, AKAP3, AKAP4, and ROPN1) in the fibrous sheath in tumor cells, in turn promoting cancer progression." (PMID 28086239, 2017). "As a component of AKAP4, FSIP1 may play a role in tumorigenesis and could therefore be a target for cancer immunotherapy." (PMID 25826084, 2015). "Our work proved that FSIP1 promoted EMT by regulating fibroblasts in the TME, thereby promoting the carcinogenic activity of cancer cells in proliferation, invasion, and migration." (PMID 38737444, 2024).
tumor (6 papers, 2015 to 2024). "FSIP1 was associated with pTNM pathological stage, tumor location, and neural invasion." (PMID 35692888, 2022). "Our results indicate that the prediction model constructed by tumor T classification, N classification, and FSIP1 expression level can predict the prognosis of patients with GC." (PMID 35692888, 2022). "Patients with high expression of FSIP1 were correlated with tumor pathological stage (P < 0.001), tumor location (P = 0.003), and neural invasion (P = 0.012)." (PMID 35692888, 2022). "The difference between the tumor volumes in the vehicle treated and docetaxel treated mice (Δ value) were calculated for both FSIP1-sgRNA and GFP-sgRNA derived xenograft cohorts." (PMID 30814489, 2019). "FSIP1 mRNA and protein expression were measured in NSCLC tissues and non-tumor adjacent tissues (NATs), and Harrell's concordance index (c-index) was used to evaluate the ability of FSIP1 to predict prognosis." (PMID 28086239, 2017). "It has also been shown that FSIP1 functions in the regulation of chromosome segregation in tumor cells." (PMID 25826084, 2015). "This also indicated that FSIP1 is closely related to tumor progression." (PMID 38737444, 2024). "These suggested to us that FSIP1 plays a major part in tumor progression." (PMID 38737444, 2024). "We also quantified FSIP1 expression in serum and wound fluid to determine whether FSIP1 could be secreted into the wound or blood, which may have an impact on the dissemination of residual tumor cells after surgery." (PMID 25826084, 2015). "Furthermore, FSIP1 expression level in the tumor significantly predicted distant metastasis in prognosis analysis." (PMID 25826084, 2015). "Additionally, both subcutaneous xenograft and lung metastatic models validated the hypothesis that FSIP1 inhibition significantly repressed tumor growth whilst augmenting docetaxel sensitivity in the nude mice." (PMID 30814489, 2019). "Further functional study is needed to address how FSIP1 might regulate tumor metastasis." (PMID 25826084, 2015). "In this study, GO and KEGG analysis demonstrated that FSIP1 was related to EMT, which was an important signal pathway for tumor cell metastasis, and was involved in tumor cell proliferation and propagation." (PMID 38737444, 2024). "Significant lung metastasis was seen in all mice (5 of 5) who received vector cells, while tumor cells had not metastasized to the lung in any of the mice transplanted with the FSIP1 knockout cells." (PMID 30814489, 2019). "When the data were analyzed according to the expression status of ER, PR, Her-2, and Ki67 in each tumor, significant survival differences were observed between FSIP1-positive status and FSIP1-negative status in patients with ER-positive and Her-2 negative tumors (p = 0.016 and 0.009, respectively)." (PMID 25826084, 2015).
adenocarcinoma (1 paper, 2017). A common cancer characterized by the presence of malignant glandular cells. "While in adenocarcinoma, FSIP1 expression was predominantly in the cytoplasm." (PMID 28086239, 2017).
FSIP1 also shares sentences with these, for which no sentence is quoted: mitochondrial disease (9 papers); HSD10 mitochondrial disease (7); Alzheimer disease (4); cardiomyopathy (3); Intellectual disability (2); metabolic disease (2); neurodegenerative disease (2); Parkinson disease (2); adrenal gland cancer (1); adrenal gland tumor (1); Ataxia (1); benign tumors (1); bone cancer (1); Cerebral ischemia (1); Choreoathetosis (1); developmental delays (1); developmental disabilities (1); ductal carcinoma in situ (1); Encephalopathy (1); epilepsy (1); invasive breast carcinoma (1); lactic acidosis (1); Onset (1); pheochromocytoma (1); prostate carcinoma (1); prostate tumor (1); Stroke (1); viral infection (1).